SH3BP5L (SH3 binding domain protein 5 like)
Description:
Functions as a guanine nucleotide exchange factor (GEF) for RAB11A.
Synonyms: KIAA1720
Tractability: PROTAC: ubiquitination databases record sites on it; its protein half-life has been measured.
Gene: Protein-coding gene on chromosome 1 (248,810,446 to 248,826,522, reverse strand). Ensembl gene ENSG00000175137.
Subcellular location (Human Protein Atlas): Golgi apparatus; Nucleoplasm; Vesicles
Gene Ontology:
Molecular function: guanyl-nucleotide exchange factor activity; protein binding; protein kinase inhibitor activity
Biological process: intracellular signal transduction
Cellular component: cytoplasm
Genetic constraint (gnomAD): Loss-of-function variants: 18 observed, 42.3 expected, observed/expected ratio (o/e) 0.43, 90% interval 0.29 to 0.63. The upper end of that interval is the gene's LOEUF score, 0.63, which puts it in group 2 of 6, group 1 being the genes least tolerant of losing a copy. Missense variants: 471 observed, 540.8 expected, observed/expected ratio (o/e) 0.87, 90% interval 0.81 to 0.94. Synonymous variants: 229 observed, 231 expected, observed/expected ratio (o/e) 0.99, 90% interval 0.89 to 1.11.
Homologues: Orthologues: chimpanzee SH3BP5L (99% identical), rat Sh3bp5l (96% identical), mouse Sh3bp5l (95% identical), pig SH3BP5L (94% identical), dog SH3BP5L (93% identical), guinea pig SH3BP5L (92% identical), rabbit SH3BP5L (91% identical), macaque SH3BP5L (70% identical), zebrafish sh3bp5lb (63% identical), tropical clawed frog sh3bp5l (61% identical), zebrafish sh3bp5la (53% identical), Drosophila melanogaster pcs (37% identical), and 2 more. Paralogues in human: SH3BP5 (34% identical).
Diseases named in the same sentence as SH3BP5L in open-access papers:
SH3BP5L is named in the same sentence as 5 diseases in open-access papers, as found by Europe PMC text mining. Sharing a sentence is not in itself a finding about the gene and the disease. The quoted sentences say what the papers report.
breast carcinoma (2 papers, 2023 to 2026). "In a different cell type, BT20 breast cancer cells, knockdown of Rab4a, Rab4b, Rab11a, Rab11b or Rab25 significantly decreased motility, as did knockdown of CLINT1 or SH3BP5L." (PMID 37232246, 2023).
depression (1 paper, 2021). "Sh3bp5l was down-regulated in gut microbiota-dysbiosis-induced depression mice." (PMID 35087377, 2021).
epilepsy (1 paper, 2025). A brain disorder characterized by episodes of abnormally increased neuronal discharge resulting in transient episodes of sensory or motor neurological dysfunction, or psychic dysfunction. "We found that CDC25B, DNMT1, GZMA, MTX1, and SSH2 expression decreases epilepsy risk, whereas FGD3, RAF1, and SH3BP5L increase it." (PMID 39753851, 2025).
triple-negative breast carcinoma (1 paper, 2026). An invasive breast carcinoma which is negative for expression of estrogen receptor (ER), progesterone receptor (PR), and human epidermal growth factor receptor 2 (HER2). "High SH3BP5L expression marked an advanced tumor stage, distant metastasis, and poor prognosis, with significant associations in human epidermal growth factor receptor 2-positive (HER2+) and triple-negative breast cancer (TNBC)." (PMID 41623179, 2026).
SH3BP5L also shares sentences with these, for which no sentence is quoted: tumor (1 paper).